STAT6 (signal transducer and activator of transcription 6)
Diseases named in the same sentence as STAT6 in open-access papers (continued):
Sharing a sentence is not in itself a finding about the gene and the disease.
colitis (continued). "Data from a study focusing on spontaneous resolution of inflammation in a murine trinitrobenzene sulfonic acid-induced colitis model revealed that colitis-induced secretion of IL-13 led to the inactivation (i.e., Ser9 phosphorylation) of GSK3β via the STAT6-driven activation of p38." (PMID 32231133, 2020). "Here, we evaluated the anti-inflammatory Trimethylglycine and the Signal transducer and activator of transcription (STAT6) inhibitor AS1517499, as possible adjuvants to 5-FU in already established cancers, using a model of colitis-associated colon cancer (CAC)." (PMID 32244885, 2020). "The IL-4 treatment started at height of infection and three days of treatment led to that the pathogen was removed from the colonic epithelial surface earlier than in vehicle or Stat6 inhibitor treated mice and this was accompanied by a 30% decrease in colitis." (PMID 30665337, 2019). "To assess whether iTregs generated in the absence or inhibition of STAT6 remain stable under in vivo inflammatory conditions, we intravenously transferred FACS-sorted control iTregs, AS-iTregs, or STAT6−/− iTregs (3 × 105 cells) into mice during AOM/DSS-induced colitis." (PMID 41203944, 2025). "Therefore, by combining network pharmacology with results reported in the literature, we were able to further study changes in the P38MAPK, ERK, JNK, NF-κB, and STAT6 signaling pathways, which are intimately associated with macrophage polarization in DSS-induced colitis." (PMID 35387334, 2022). "Also, other investigators showed that increased STAT6 could play a significant role in colitis by affecting the IL-13 production, whereas a decrease in STAT6 could prevent apoptosis and disruption of cell membrane integrity." (PMID 35240996, 2022). "Thus, loss of Stat6 caused more severe colitis and increased tumor load, however loss-of-initiated Stat6−/− IEC prevented tumor formation in the absence of overt inflammation." (PMID 30353167, 2019). "However, STAT6 was found to be dispensable in a TCRα−/− colitis model." (PMID 29910812, 2018). "The pivotal role of STAT6 signaling in Tregs development during colitis and CAC has been highlighted in STAT6 knockout mice, which exhibit increased levels of suppressive Tregs in the early stages of CAC, correlating with reduced tissue damage." (PMID 41203944, 2025). "Luteolin-7-glucopyranoside exhibits antioxidant and anti-inflammatory properties by modulating the JAK1/STAT6/SOCS1 pathway and alleviating inflammatory diseases, such as colitis." (PMID 40283142, 2025). "In summary, WMW interferes with the p38MAPK, NF-κB and STAT6 signaling pathways to regulate M1/M2 polarization in macrophages, thereby protecting mice against DSS-induced colitis." (PMID 35387334, 2022). "By weakening the function of intestinal epithelial barrier, non-hematopoietic STAT6 increases intestinal permeability, aggravates experimental colitis induced by dextran sulphate sodium (DSS) and further leads to CAC30." (PMID 38831059, 2024). "STAT6, GATA3, and SMAD proteins are also required for Th9 differentiation and may be involved in Th9-mediated colitis." (PMID 29910812, 2018). "It is noteworthy that oxazolone-induced colitis in mice lacking IL-4Ra or STAT6 was significantly improved." (PMID 28316599, 2017). "The anti-colitis efficacy of a T. versicolor extract has also been demonstrated in an experimental colitis mice model, in which the oral administration of the extract suppressed the gene expression of STAT1, STAT6, IL-4, and IFN-γ." (PMID 24019869, 2013). "We had demonstrated in vitro that LBP regulated M1/M2 macrophage polarization by modulating the STAT1 and STAT6 pathways, and also found that LBP could regulate macrophage polarization in DSS-induced colitis mice by the detection of the expression of M1 or M2 marker in colon tissue." (PMID 37144216, 2023).
colitis (continued). "Because STAT6 activation is a critical signaling node for BHB’s regulating M2 macrophage polarization, we speculated that it is also required for BHB therapeutic role during colitis development." (PMID 35422042, 2022). "In addition to STAT6, the shown M2 phenotype can also be promoted through the activation of STAT3, as supported by our results of increased STAT3 phosphorylation in CD26−/− mice during colitis development." (PMID 35628317, 2022). "Building on our in vitro findings that STAT6 inhibition enhances the stability and suppressive function of iTregs, we next investigated whether in vivo administration of the STAT6 inhibitor AS1517499 could similarly enhance Treg activity and attenuate inflammation in a model of acute colitis." (PMID 41203944, 2025). "Finally, the expansion of Foxp3+IFN-γ+ Tregs following STAT6 inhibition during acute colitis may reflect an adaptive regulatory phenotype rather than pathogenic plasticity." (PMID 41203944, 2025). "Therefore, we hypothesized that Stat6−/− mice should be protected from AOM-induced tumorigenesis when this model was done in the absence of DSS-induced colitis." (PMID 30353167, 2019). "However, the role of STAT6 and SMADs on IL-9 production in colitis has not been examined." (PMID 29910812, 2018).
colon carcinoma (35 papers, 2002 to 2026). "On the contrary, high Stat6 activity has been associated with the invasive and metastatic capacity of colon cancer cells, mainly due to induction of an epithelial to mesenchymal transition (EMT) phenotype." (PMID 32927726, 2020). "Furthermore, STAT6 has been implicated in the prevention of apoptosis in human colon cancer cells, and its expression in these cells positively correlates with increased invasive and metastatic capabilities." (PMID 21595984, 2011). "The overexpression of mCRPs in colon cancer leads to the upregulation of STAT3/STAT6/p38 MAPK signaling." (PMID 38671854, 2024). "As a synthetic vitamin A derivative, fenretinide suppresses M2-macrophages by inhibiting STAT6 phosphorylation and further preventing the tumorigenesis of colon carcinoma." (PMID 37342343, 2023). "Accordingly, it has been shown that IL-13 induces epithelial-mesenchymal transition (EMT) via STAT6 in colon cancer cell lines, a process that was reversed by propofol, due to the ability of this anesthetic agent to suppress the expression of STAT6." (PMID 33371444, 2020). "In order to explore further the mechanism associated with the remarkable effect observed by the Trimethylglycine therapy, we analyzed the inhibition of STAT6 phosphorylation in epithelial cells by using HCT-116 human colonic cancer cells." (PMID 32244885, 2020). "Here we evaluated the role of STAT6 inhibition activity in established colon tumors in order to assay its possible adjuvant effect on 5-FU therapy." (PMID 32244885, 2020). "STAT6 activation participates in the malignancy of different types of cells, including colon cancer cells, prostate, breast, and mediastinal large B-cell lymphoma." (PMID 32244885, 2020). "In two recent reports, it has been found that STAT6 protein plays a fundamental role in early colon cancer development, in which STAT6−/− mice decreased tumor growth by 70%." (PMID 32244885, 2020). "In vitro assays on human colon cancer cells showed that Trimethylglycine also reduced STAT6-phosphorylation." (PMID 32244885, 2020). "Taken together, these data provide evidence demonstrating that IL-4 and IL-13 upregulate NOX1 in colon cancer cells though the IL-4R/STAT6 pathway, and that GATA3 plays an important role in the transcriptional regulation of NOX1." (PMID 28498822, 2017). "We previously demonstrated that STAT6 mRNA expression levels decreased in CD11b+ myeloid cells from colon tumor-bearing HDC−/− mice compared with WT control mice." (PMID 28272448, 2017). "Colonic cancer HT-29 cells with high STAT6 expression phenotype (STAT6high) exhibited low constitutive expression of STAT6-negative regulators SOCS1 and SHP1 because of gene hypermethylation, with the opposite findings in STAT6null cells." (PMID 24757565, 2014). "Nevertheless, STAT6 is over-expressed and active in numerous malignancies including prostate and colon cancer, lymphoma, and leukemia." (PMID 21595984, 2011). "For example, reports in the literature describe anti-apoptotic effects of STAT6 in primary B cells, Hodgkin lymphoma cells and colon cancer cells." (PMID 21595984, 2011). "Case-control studies, using more than 1550 patients with colon cancer and 750 cases of rectal cancer, demonstrated that JAK2, SOCS2, STAT1, STAT3, STAT5A, STAT5B, and STAT6 were associated with colon cancer, and that STAT3, STAT4, STAT6, and TYK2 were linked to rectal cancer." (PMID 36982677, 2023). "In colon cancer, the M2a subtype with a STAT6‐stimulated pathway plays a particular role." (PMID 38037545, 2023). "IL-4, which is abundant in the tumor microenvironment, increases survivin protein expression in human macrophages, which is in agreement with a recent report describing that survivin expression and location are regulated by IL-4 in colon cancer stem cells through a STAT6-dependent pathway." (PMID 33710603, 2021).
colon carcinoma (continued). "Inflammation provoked by obesity notably increased expression of IL-13, which in turn leads to increased expression of IL-13R1, ending up with activation of downstream phosphorylation of the transcription factor STAT6, suggesting a possible mechanism of carcinogenesis in colon cancer." (PMID 32283835, 2020). "Therefore, overall, these data point to STAT6 being a valuable target for adjuvant therapy in the treatment of an already established colon cancer triggered by a strong inflammatory component." (PMID 32244885, 2020). "Together, these data point to STAT6 as a valuable target for adjuvant therapy in colon cancer." (PMID 32244885, 2020). "Inhibition of especially STAT6 phosphorylation by platinum compounds could possibly explain the beneficial effect of oxaliplatin in colon cancer patients that were treated with moDC vaccination." (PMID 31309123, 2019). "Moreover, the number as well as the size of colonic tumors was significantly higher in Stat6−/− mice." (PMID 30353167, 2019). "Yet, in this study Stat6−/− mice developed a reduced inflammatory response and a lower number of colonic tumors, possibly due to a different experimental set up (i.e. lack of cohoused control mice or no exchange of bedding) causing changes in the intestinal microbiome." (PMID 30353167, 2019). "Studies have shown that IL-13 mediates extracellular matrix proteins (Fibronectin and collagen I) production by fibroblasts via STAT6 pathway, and aggressive colon tumors with collagen-rich stroma present mesenchymal features and stronger capability for invasion." (PMID 27533463, 2016). "Furthermore, in colonic cancer cell line HT-29 that constitutively expresses STAT6, there is downregulation of CIS and SOCS7 (in addition to SOCS1, SOCS3, and SHP1)." (PMID 24757565, 2014). "Firstly, in colorectal cancer, IL-4 induces the expression of epithelial-mesenchymal transition(EMT)-promoting proteins through signal transducer and activator of transcription 6(STAT6)-dependent transcription, thereby prompting EMT in colon cancer cells." (PMID 38840908, 2024). "In in vivo efficacy studies in colon carcinoma CT26 tumors, ExoASO STAT6 or C/EBPβ treatment results in a reduction in the expression of STAT6 and C/EBPβ in tumor‐associated CD11b+ myeloid cells." (PMID 36684102, 2023). "In contrast, the Foxp3+ cells were elevated in the colonic tumors of the STAT6−/− PC61 animals during the late stages of CAC development, compared to the STAT6−/− CAC and WT PC61 mice." (PMID 33919941, 2021). "To investigate the specific inhibition of GO-Y030, we detected the phosphorylation of STAT3, STAT1, or STAT6 induced by IL-6, IFN-γ, or IL-4 in HT29 colon cancer cell lines." (PMID 21694723, 2011). "It is reported that both IL4 and IL13 share signalling events in human colon carcinoma cell lines (HT29 and WiDr), and that both IL13 and IL4 induce phosphorylation of IL4 STAT (STAT6)." (PMID 12402156, 2002). "In this direction, we evaluated whether STAT6 inhibition using AS1517477 and Trimethylglycine as adjuvant therapies to 5-FU favored the induction of apoptosis of colon cancer cells." (PMID 32244885, 2020). "However, the direct participation of STAT6 in the treatment of colon cancer has not been fully established." (PMID 32244885, 2020). "Additionally, in colon cancer stem cells, Survivin was regulated by IL4 through STAT-6 signaling and allowscancer cells to escape chemo sensitizing, which can be explained through our study that ERS inhibition may have reduced Survivin expression via IL4." (PMID 30326660, 2018).
colorectal cancer (32 papers, 2016 to 2026). A primary or metastatic malignant neoplasm that affects the colon or rectum. "In colorectal cancer tumors, increased phosphorylation of signal transducer and activator of transcription-6 is associated with poorer patient survival." (PMID 41239618, 2025). "The influence of STAT6 on immune cell regulation and its association with different types of malignancies, including colorectal cancer, has been already investigated." (PMID 30353167, 2019). "So far, the association between STAT6 and cancer patients’ clinical outcomes was only investigated in colorectal cancer." (PMID 28536310, 2017). "Patients with colorectal cancer exhibit a significant STAT6 activity in the colonic epithelium, and STAT6 expression is associated with lower survival rates, lymph node metastasis, changes in the epithelial barrier function, and alterations in the inflammatory response." (PMID 33919941, 2021). "The findings demonstrated that 23-HBA can attenuate 5-FU resistance in colorectal cancer by inhibiting M2 macrophage polarization via STAT6 signaling." (PMID 38554148, 2024). "When comparing the combined and separate groups, the 5-FU IC50 was decreased from 7.473 ug/ml to 2.482 ug/ml, revealing that STAT6 can play an important role in the resistance of colorectal cancer cells to 5-FU." (PMID 38419894, 2024). "Clinical evidence reveals a positive correlation between high levels of STAT6 expression and poor clinical outcomes in colorectal cancer patients." (PMID 38554148, 2024). "The STAT6 signaling pathway is highly activated in many tumors and has been shown to promote tumor metastasis in colorectal cancer and melanoma carcinoma." (PMID 37175092, 2023). "There is research to develop STAT6 inhibitors due to the implication of STAT6 signalling in colorectal cancer, melanoma and allergic lung diseases." (PMID 36337046, 2022). "Upregulating RP11-468E2.5 curtails the JAK/STAT signaling pathway by targeting two molecules, STAT5 and STAT6, and finally attenuates cell proliferation but boosts cell apoptosis in colorectal cancer." (PMID 36704346, 2022). "Our data agree with previous results in colorectal cancer, where it was shown that high levels of STAT6 phosphorylation lead to apoptosis resistance when compared to STAT6-defective cell phenotypes." (PMID 32244885, 2020). "A recent study demonstrated that IL-13 can induce an aggressive type of colorectal cancer by enhancing the expression of the epithelial–mesenchymal transition-promoting factor ZEB1 through the STAT6-dependent pathway." (PMID 33352852, 2020). "Furthermore, we propose that the mechanism by which 23-HBA can overcome 5-FU resistance in colorectal cancer involves inhibition of M2 macrophage polarization via STAT6 signaling." (PMID 38554148, 2024). "Consequently, pharmacological inhibition of the STAT6 pathway emerges as a feasible strategy to regulate macrophage polarization, potentially impeding tumor progression and reducing chemoresistance in colorectal cancer." (PMID 38554148, 2024). "High STAT6 expression correlates with worse prognosis in colorectal cancer and prostate cancer." (PMID 37377751, 2023). "In an IL-4-dependent manner Stat6 has been suggested to promote colorectal cancer due to its ability to polarize myeloid cells in a wound–healing/tumor-promoting alternative phenotype, which differentiates these cells from the tumor-suppressing IFNγ-mediated classical activation phenotype." (PMID 30353167, 2019). "Additionally, HEX loaded with an antisense oligonucleotide (ASO) targeting STAT6 selectively silenced expression of this transcription factor in colorectal cancer and HCC mouse models; combined with anti-PD1 immunotherapy, this led to greater than 90% inhibition of tumor growth." (PMID 36591444, 2022). "In colorectal carcinoma, elevated CD44V6 promoted cancer progression to later stages through activating the Stat6 signaling pathway." (PMID 36292918, 2022).
colorectal cancer (continued). "IL-4 induced STAT6 signaling in promoting cell proliferation/growth and cell apoptosis resistance and induced epithelial-mesenchymal transition (EMT) in colorectal cancer cells via E2F1/SP3/STAT6 axis." (PMID 33506057, 2021). "In colorectal cancer cells, IL13 induced epithelial-to-mesenchymal transition through the STAT6 pathway and was reversed with knock-down of IL13Rα1." (PMID 33419470, 2021). "We then wondered if HSP110 inhibition could also alter STAT6 signaling, since we previously showed that HSP110 has a role in STAT3 activation in colorectal cancer." (PMID 38773631, 2024).